KAT6A (lysine acetyltransferase 6A)
Description:
Histone acetyltransferase that acetylates lysine residues in histone H3 and histone H4 (in vitro). Component of the MOZ/MORF complex which has a histone H3 acetyltransferase activity. May act as a transcriptional coactivator for RUNX1 and RUNX2. May play a role in leukemogenic gene transcription.
Synonyms: MYST-3; MOZ; MYST3; RUNXBP2; ZNF220; ARTHS; MRD32; ZC2HC6A
Tractability: Small molecule: a structure with a bound ligand is known; a high-quality ligand is known; it has a high-quality binding pocket. PROTAC: UniProt records ubiquitination sites on it; ubiquitination databases record sites on it; its protein half-life has been measured; a small molecule that binds it is known.
Target class: Enzyme
Chemical probes: PF-9363 (high quality), WM 1119 (high quality)
Gene: Protein-coding gene on chromosome 8 (41,929,479 to 42,051,998, reverse strand). Ensembl gene ENSG00000083168.
Subcellular location: Nucleus; Nucleus, nucleolus; Nucleus, nucleoplasm; Nucleus, PML body
Subcellular location (Human Protein Atlas): Nuclear speckles; Cytosol; Nucleoli
Pathways (Reactome):
Chromatin organization: HATs acetylate histones
Gene Ontology:
Molecular function: acetyltransferase activity; DNA binding; DNA-binding transcription factor binding; histone acetyltransferase activity; histone H3K14 acetyltransferase activity; histone H4K12 acetyltransferase activity; histone H4K16 acetyltransferase activity; histone H4K5 acetyltransferase activity; histone H4K8 acetyltransferase activity; protein binding; protein-lysine-acetyltransferase activity; transcription coactivator activity; zinc ion binding; chromatin binding; histone H3 acetyltransferase activity; transcription coregulator activity
Biological process: cellular senescence; myeloid cell differentiation; negative regulation of DNA-templated transcription; positive regulation of DNA-templated transcription; regulation of DNA-templated transcription; chromosome organization; regulation of developmental process; regulation of hemopoiesis; regulation of transcription by RNA polymerase II; nucleosome assembly; positive regulation of gene expression
Cellular component: MOZ/MORF histone acetyltransferase complex; nuclear speck; nucleolus; nucleus; PML body; nucleoplasm; nucleosome
Genetic constraint (gnomAD): Loss-of-function variants: 7 observed, 159.35 expected, observed/expected ratio (o/e) 0.0439, 90% interval 0.024 to 0.083. The upper end of that interval is the gene's LOEUF score, 0.083, which puts it in group 1 of 6, group 1 being the genes least tolerant of losing a copy. Missense variants: 1,883 observed, 2,294.5 expected, observed/expected ratio (o/e) 0.82, 90% interval 0.79 to 0.85. Synonymous variants: 800 observed, 822.96 expected, observed/expected ratio (o/e) 0.97, 90% interval 0.92 to 1.03.
Gene-disease validity (ClinGen):
ClinGen rates the evidence that KAT6A causes each of these diseases.
syndromic intellectual disability (autosomal dominant): Definitive. A intellectual disability that is part of a larger syndrome.
Cancer hallmarks: invasion and metastasis (promotes); escaping programmed cell death (promotes); proliferative signalling (promotes); escaping immune response to cancer (promotes); change of cellular energetics
Homologues: Orthologues: chimpanzee KAT6A (99% identical), macaque KAT6A (99% identical), dog KAT6A (94% identical), guinea pig KAT6A (92% identical), mouse Kat6a (89% identical), rat Kat6a (89% identical), tropical clawed frog kat6a (63% identical), zebrafish kat6a (60% identical), Drosophila melanogaster tth (4% identical), Drosophila melanogaster d4 (3% identical), Caenorhabditis elegans dpff-1 (3% identical). Paralogues in human: KAT6B (53% identical), KAT7 (12% identical), KAT5 (10% identical), RSF1 (10% identical), KAT8 (10% identical), PHF10 (6% identical), DPF2 (4% identical), DPF3 (4% identical), DPF1 (4% identical).
Diseases named in the same sentence as KAT6A in open-access papers:
KAT6A is named in the same sentence as 93 diseases in open-access papers, as found by Europe PMC text mining. Sharing a sentence is not in itself a finding about the gene and the disease. The quoted sentences say what the papers report.
breast carcinoma (27 papers, 2010 to 2025). "Proto‐oncogenes that are frequently overexpressed and associated with poor prognosis—such as KAT6A in breast cancer—are generally considered attractive therapeutic targets or clinically actionable biomarkers." (PMID 41357671, 2025). "Metagenomic analysis of KATs in human cancers revealed that KAT6A obtained high frequencies of genomic amplification or mutation in breast cancer." (PMID 41357671, 2025). "Overexpression of KAT6A is associated with poor clinical prognosis in ER+/HER2-breast cancer patients." (PMID 40949156, 2025). "A metagenomic analysis of 37 lysine acetyltransferases across various human cancer types, with a focus on breast cancer, revealed that KAT6A is frequently subject to genomic amplification or mutation." (PMID 40949156, 2025). "The molecular mechanism underlying the oncogenic role of KAT6A in ER+/HER2− breast cancer has been explored." (PMID 41357671, 2025). "For instance, KAT6A upregulation was identified in estrogen receptor‐positive (ER+) breast cancer, which was associated with progressive development and poor clinical outcomes." (PMID 41357671, 2025). "Here, we demonstrate that KAT6A amplifies in TNBC subtype breast cancer and its amplification associates with TNBC prognosis." (PMID 34392614, 2021). "KAT6A is associated with oncogenesis in both leukemia and breast cancer, because of dysregulation of its histone acetyltransferase activity or its aberrant expression." (PMID 31888644, 2019). "An increase in KAT6A levels enhances ESR1 mRNA and ERα expression, which in turn is linked to more aggressive behaviors of ER+/HER2− breast cancer cells." (PMID 41357671, 2025). "In multiple ER+/HER2− breast cancer cell lines with KAT6A overexpression, the compounds exhibited antiproliferative effects in accordance with inhibition of H3K23Ac and ERα expression." (PMID 41357671, 2025). "In KAT6A‐overexpressed ER+/HER2− breast cancer models, KAT6A was found to bind to the promoter of ERα and increase its expression, thereby promoting tumor cell proliferation." (PMID 41357671, 2025). "The rationale is that KAT6A is overexpressed or amplified in ER+/HER2− breast cancer, which correlates with worse survival outcomes." (PMID 41357671, 2025). "KAT6A was found to be frequently amplified and/or overexpressed in breast cancer and has been correlated with worse prognosis in ER-positive breast cancer patients." (PMID 40165290, 2025). "KAT6A is situated within the 8p11‐12 amplicon, exhibiting a high prevalence of amplification, with a frequency range of 10–15% in breast cancer patients." (PMID 41357671, 2025). "The amplification of KAT6A was correlated with an unfavorable prognosis in patients with ER+/HER2− breast cancer." (PMID 41357671, 2025). "Conversely, KAT6A knockdown or inhibition attenuates breast cancer cell growth and exerts antitumor effects, encompassing a mechanism of eradicating ERα expression at the transcriptional level." (PMID 41357671, 2025). "The regulatory role of KAT6A in the TME offers insights into the development of novel therapeutic strategies regarding ICI in HR+ breast cancer." (PMID 41357671, 2025). "In KAT6A‐amplified ER+/HER2− breast cancer cell lines, including ZR‐75‐1 and CAMA‐1, ISM5043 demonstrated dose‐dependent antitumor efficacy as monotherapy, which correlated with the suppression of H3K23Ac and ERα protein levels." (PMID 41357671, 2025). "The amplification/overexpression rate of KAT6A/6B in breast cancer has been reported to reach 10%–15%." (PMID 40949156, 2025). "The functions of KAT6A have been interrogated in breast cancer preclinical models because it is located within the 8p11-p12 amplicon that is found amplified in 12–15% of breast cancers." (PMID 38824244, 2024). "Previous studies have demonstrated that KAT6A played an essential role in developing malignant diseases, such as leukemia, lung cancer, breast cancer, etc." (PMID 39129034, 2024).
breast carcinoma (continued). "Subsequently, the oncogenic role of KAT6A has been highlighted in leukemia, breast cancer, and glioma." (PMID 36900344, 2023). "Previous studies have suggested that KAT6A plays an oncogenic role in breast cancer 16 and leukemia 18-19." (PMID 33995658, 2021). "We further assessed KAT6A expression in a nontumorigenic epithelial cell line MCF‐10A and various breast cancer cell lines and revealed that compared with MCF‐10A cells, KAT6A was highly expressed in all tested breast cancer cells." (PMID 34392614, 2021). "Lysine acetyltransferase 6A (KAT6A) is a MYST-type histone acetyltransferase (HAT) enzyme identified as an oncogene in breast cancer, glioblastoma and leukemia." (PMID 33995658, 2021). "Previous research revealed that histone acetyltransferase KAT6A played key role in maintaining the ability of self-renewal and activity of luminal breast cancer stem cell." (PMID 27768723, 2016). "The transcriptional interaction between KAT6A and ESR1, along with the high frequency and the critical role of ESR1 mutations in ER+ breast cancer, has prompted researchers to investigate the potential impact of ESR1 mutations on the efficacy of KAT6 inhibitors." (PMID 41357671, 2025). "SMAD3 was identified as a non-histone substrate of lysine acetyltransferase 6 A (KAT6A) and the acetylation of SMAD3 at K20 and K117 by KAT6A leads to enhanced breast cancer stem-like cell stemness, myeloid-derived suppressor cell recruitment, and triple-negative breast cancer (TNBC) metastasis." (PMID 40164592, 2025). "Furthermore, in ER+/HER2− breast cancer following progression on CDK4/6i, genetic alterations associated with KAT6A inhibition were found to be enriched in cell cycle and associated pathways, such as the E2F pathway." (PMID 41357671, 2025). "KAT6A is also amplified as part of the 8p11 amplicon in 10-15% of breast cancers." (PMID 35774123, 2022). "For instance, given the KAT6A amplification in 10-15% of breast cancers, novel compounds against KAT6A/KAT68 (PF-9363) have been developed and analyses in preclinical models demonstrate potent anti-tumor activity in ER+ breast cancer cells and xenografts with KAT6A dysregulation." (PMID 35774123, 2022). "In addition, KAT6A is thought to be an oncogene in human cancers, including breast cancer 16, glioma 17 and leukemia 18-20." (PMID 33995658, 2021). "In addition, targeting KAT6A using WM‐1119 inhibitor markedly improved the efficiency of the PD‐L1 immunotherapy using an orthotopic xenograft model of breast cancer metastasis." (PMID 34392614, 2021). "Taken together, these data demonstrate that KAT6A‐induced acetylation of SMAD3 promoted metastasis not only by enhancing breast cancer stem‐like cell properties but also by inducing the MDSCs recruitment by persistent production of immune response‐related cytokines." (PMID 34392614, 2021). "The KAT6A/B inhibitor PF-07248144 is currently being validated for safety, tolerability, and clinical efficacy in combination with either Fulvestrant, letrozole + palbociclib, or PF-07220060 + Fulvestrant in patients with advanced or metastatic solid tumors, including breast cancer (NCT04606446)." (PMID 40949156, 2025). "Thus, we investigated whether targeting KAT6A by using an inhibitor WM‐1119 will improve the efficacy of PD‐L1 immunotherapy in treating breast cancer." (PMID 34392614, 2021). "Based on recently released preclinical data, the OP compounds, which potently inhibit both KAT6A and KAT6B, exhibit robust antitumor efficacy in ER+/HER2− breast cancer." (PMID 41357671, 2025). "In ER+/HER2− cell lines and breast cancer PDX models, CTx‐648 demonstrated potent and selective inhibitory activity against the KAT domains of KAT6A, yielding strong and tolerable on‐target in vivo efficacy involving tumor regression with minimal toxicity." (PMID 41357671, 2025). "KAT6A overexpression is highly correlated with gene amplification, suggesting their similar roles in clinical outcomes of ER+/HER2− breast cancer." (PMID 41357671, 2025).
breast carcinoma (continued). "KAT6A and its paralog KAT6B have emerged as druggable targets for the treatment of malignancies, especially for breast cancer." (PMID 41357671, 2025). "Overall, KAT6A and KAT6B are attractive and desirable epigenetic targets for therapeutic leverage in human disease, particularly in ER+/HER2− breast cancer." (PMID 41357671, 2025). "High expression of KAT6A has been shown to result in poor survival outcomes in ER+ breast cancer, indicating that KAT6A functions as an oncogene in ER+/HER2− breast cancer." (PMID 41357671, 2025). "KAT2B, EP300, KAT6A (MYST family), and KAT2A (GNAT family) are recruited to ER-responsive promoters and are critical for estrogen-dependent proliferation of ER-positive breast cancer cells." (PMID 40165290, 2025). "Inhibition of histone lysine acetyltransferases (KATs) KAT6A and KAT6B has shown antitumor activity in estrogen receptor-positive (ER+) breast cancer preclinical models." (PMID 38824244, 2024). "An orally bioavailable KAT6A and 6B inhibitor that selectively inhibits the catalytic activity of KAT6A and KAT6B was recently shown to elicit on-target antitumor activity in vivo in ER+ breast cancer and other cancer types in preclinical studies." (PMID 38824244, 2024). "To explore the putative targets regulated by KAT6A in breast cancer metastasis, we purified the KAT6A complex from MDA‐MB‐231 cells transduced with Flag‐tagged KAT6A and performed MS analysis." (PMID 34392614, 2021). "We also found that our deep-learning classifier predicted well (AUC > 0.65) on the CNA status in breast cancer, including six genes of FGFR1, EIF4EBP1, KAT6A, HEY1, ZNF217, and RAB25." (PMID 34556802, 2021). "PF-07248144 is the KAT6A/KAT6B inhibitor currently in clinical trials, and the results from the phase 1 clinical trial were recently published and showed durable antitumor effects in metastatic ER-positive HER2-negative breast cancer." (PMID 40165290, 2025). "Regarding transcriptional aspects, KAT6A mRNA has been observed to be overexpressed in ER+ breast cancer, accounting for about 15% of breast cancers and a higher percentage of 22% in ER+/HER2− breast cancer." (PMID 41357671, 2025). "KAT6A and KAT6B represent attractive epigenetic targets in the context of breast cancer biology." (PMID 41357671, 2025). "In ER+/HER2− breast cancer cell models, a significant correlation was observed between the cell line sensitivity (AUC) of a KAT6‐specific inhibitor and the BRPF1 dependency score of KAT6A as compared with KAT6B." (PMID 41357671, 2025). "KAT6A is required for H3K9ac at specific gene loci in mouse embryonic fibroblasts, in E10.5 embryos and tissue and in AML cells, as well as for H3K23ac in glioblastoma cells and breast cancer cells." (PMID 39537341, 2025). "KAT6A promotes SMAD3 binding to oncogenic chromatin modifier TRIM24 and disrupts its interaction with the tumor suppressor TRIM33, which lead to the tumor cell metastasis in breast cancer." (PMID 35430805, 2022). "Given that both KAT6A and TGF‐β/SMAD3 are activated in many cancers, including breast cancer, we investigated potential crosstalk between these two intensively studied oncogenic pathways and determined the biological consequence of the KAT6A–SMAD3 signaling in TNBC metastasis." (PMID 34392614, 2021). "Recent progress in drug discovery has led to the development of dual KAT6A and KAT6B inhibitors with potent antitumor efficacy and selectivity in both preclinical and clinical settings, supporting KAT6 as a druggable, promising target for the treatment of cancers, particularly breast cancers." (PMID 41357671, 2025).
breast carcinoma (continued). "However, another emerging study showed that drug sensitivity to the KAT6 inhibitor was mediated by ER expression in ER+/HER2− breast cancer models, rather than KAT6A protein levels." (PMID 41357671, 2025).